CRP (C-reactive protein)
Diseases named in the same sentence as CRP in open-access papers (continued):
Sharing a sentence is not in itself a finding about the gene and the disease.
Insulin resistance (continued). "The data of the current study demonstrate an increase in CRP and IL-6 levels in obese subjects, which could highlight the marked inflammatory process that is linked to insulin resistance in obese subjects." (PMID 32708841, 2020). "However, there are data on the association of an elevated level of CRP with rising insulin resistance." (PMID 32326243, 2020). "Furthermore, it is likely that hypomagnesemia causes the release of inflammatory cytokines and C-reactive protein and promotes insulin resistance." (PMID 33282857, 2020). "Increased inflammatory biomarkers i.e. CRP and fibrinogen, which are associated with increased risk of cardiovascular disease and insulin resistance, and their association with reduced DPA has been previously shown in individuals with COPD and community dwellers." (PMID 32138714, 2020). "Moreover, it was established that the level of CRP more than 2.53 μg/mL in women (median age of 39 years, p < 0.001) raises the risk of insulin resistance 2.18-fold higher." (PMID 32326243, 2020). "Moreover, available evidence has found that insulin resistance in COPD patients is associated with inflammation mediators such as C-reactive protein (CRP), interleukin-6 (IL-6) and tumour necrosis factor–α." (PMID 32393205, 2020). "Furthermore, they presented lipid peroxidation and protein oxidation associated with insulin resistance with hyperinsulinemia and increased serum levels of CRP." (PMID 32348424, 2020). "Moreover, VAT associated with insulin resistance and markers of inflammation, such as psoriasis severity, hs-CRP, and GlycA (all P < 0.05)." (PMID 33104056, 2020). "Moreover, insulin resistance due to high insulin level is also associated with an increased inflammatory condition, including elevated CRP." (PMID 32872655, 2020). "PI-ART was associated with dyslipidemia, insulin resistance, high CRP, and increased IMTc." (PMID 29320547, 2018). "The changes described in the preliminary results confirm prior studies, including the higher levels of leptin and ghrelin, the increase in the inflammatory/cardiovascular risk marker, CRP, and the presence of insulin resistance in the subjects with higher BMI levels." (PMID 30400254, 2018). "Previous studies had suggested that different variables recorded on admission were associated with poor outcome in stroke patients, for example insulin resistance, vitamin D deficiency or 25-hydroxyvitamin D, fatty acid-binding protein 4, C-reactive protein, and homocysteine." (PMID 30038059, 2018). "Insulin resistance has been associated with both serum IL-6 and CRP levels in previous studies, and concomitant improvements (reductions) in these parameters have been observed following exercise training for 12 weeks in obese subjects, whereas TRACP-5a titers remained elevated." (PMID 29100456, 2017). "Based on the correlation analysis between weight loss and metabolic changes, the annual declines in CRP, insulin, triglyceride, blood sugar, and insulin resistance index were positively correlated with weight loss, and the correlation coefficients were statistically significant." (PMID 28115972, 2017). "In addition to vascular calcification, elevated levels of TAP have been associated with high C reactive protein, insulin resistance, and 25-OH vitamin D deficiency." (PMID 28168054, 2017). "As the G/C genotype of SREBP-2 is significantly associated with Serum levels of TG, elevated CRP, fasting insulin and homeostasis model assessment for insulin resistance levels, it can be a potential explanation for the close relationship between IR, TG, CRP and SREBP-2 polymorphism." (PMID 26965314, 2016). "Several cross-sectional studies showed that insulin resistance and type 2 diabetes are associated with higher levels of C-reactive protein (CRP), interleukin-6 (IL-6), interleukin-1β, and tumor necrosis factor-α (TNF-α), which are markers of subclinical systemic inflammation." (PMID 27034691, 2016).
Insulin resistance (continued). "It has been demonstrated that obesity and insulin resistance are associated with a proinflammatory state, which may be mediated by cytokines and subsequently cause elevated levels of CRP that might predispose to an increased risk of type 2 diabetes." (PMID 26963617, 2016). "miR-196a2 and miR-499 could regulate annexin A1 and CRP, which are also the general causes of cerebral ischemia and associated with elevated blood pressure, BMI, insulin resistance, and triglycerides." (PMID 25658319, 2015). "IL-6 and CRP may contribute to MS risk, and a sharp increase in FFA can cause both insulin resistance (IR) in the liver, increase the expression of proinflammatory cytokines such as IL-6, and stimulate the liver to secrete CRP." (PMID 26246695, 2015). "Inflammation and insulin resistance have been linked and the impact of fitness and fatness on CRP might be indirect via insulin resistance." (PMID 26075745, 2015). "Further investigation of the association between CRP and markers of insulin resistance such as HOMA-IR is required to underpin this hypothesis." (PMID 25994228, 2015). "We proposed that ferritin in combination with CRP may cause an undesirable inflammatory environment leading to insulin resistance." (PMID 26870128, 2015). "Furthermore, thigh IMAT was significantly associated with increased systemic levels of inflammatory cytokines and C-Reactive Protein, which have been linked to insulin resistance, type 2 diabetes and age-related sarcopenia." (PMID 25051047, 2014). "Insulin resistance, hyperandrogenemia, and elevated serum CRP as an inflammatory marker in PCOS could be the cause of hearing loss in especially extended high frequencies." (PMID 24194682, 2013). "We therefore undertook a meta-analysis of randomized clinical studies that evaluated effects of changing whole and low fat dairy food intake in healthy adults on a broad range of cardio-metabolic risk factors including weight, insulin resistance, lipids, blood pressure and c- reactive protein (CRP)." (PMID 24146877, 2013). "A recent study found that plasma levels are strongly associated with dairy fat consumption and also with broad health benefits—reduced incidence of new-onset diabetes, favorable CVD risk profile, reduced insulin resistance and inflammation (C-reactive protein), and slightly lower body fat." (PMID 24349282, 2013). "Among them, insulin resistance has been shown to be the most important, associated with a chronic state of subclinical inflammation, and characterized by increased serum concentrations of C-reactive protein." (PMID 23091306, 2012). "In conclusion, our results support the notion that n-3 PUFA may play a contributing role in triggering insulin resistance and serum levels of CRP by interacting with a genetic variant at GCKR gene locus." (PMID 21674002, 2011). "Second, subjects taking some antidiabetic and statin agents were not excluded from our study, which might have influenced the association of CRP levels and might have also affected the association of CRP with insulin resistance in the multivariable analysis." (PMID 21167068, 2010). "Moreover, hepatic dysfunction associated with insulin resistance may alter the acute-phase protein production profile, favoring CRP synthesis over Hp." (PMID 40944271, 2025). "Additionally, n-3 polyunsaturated fatty acids (PUFA) may play a contributing role in triggering insulin resistance and serum levels of CRP by interacting with a rs1260326-P446L genetic variant at GCKR." (PMID 38918799, 2024). "Numerous large epidemiological studies have examined the relationship between CRP and incident T2D, some of them showing a positive association, while others demonstrated nonsignificant results after adjustment for the markers of adiposity and insulin resistance." (PMID 39335474, 2024).
Insulin resistance (continued). "It was clearly demonstrated that the elevated serum CRP concentration is associated with higher fasting insulin and glucose and HbA1c levels, suggesting a possible role of inflammation in processes closely related to the MetS such as insulin resistance and glucose intolerance." (PMID 39766234, 2024). "Alternatively, the drop in postpartum insulin resistance might result from the weight-loss-associated attenuation of the inflammatory state, as CRP levels in the pGDM women were significantly decreased compared to those found during pregnancy with and without GDM." (PMID 39684804, 2024). "However, CRP could still signal inflammation, potentially exacerbating conditions linked to islet dysfunction like insulin resistance and impaired glucose metabolism, suggesting BPA-induced inflammation may indirectly harm pancreatic islets over time." (PMID 38580733, 2024). "Therefore, we studied the connection between CRP deficiency and insulin resistance in PCOS rats." (PMID 37660067, 2023). "Based on the previous literature, we hypothesized that metabolic risk factors (insulin resistance, BMI, serum cholesterol values or high sensitivity C-reactive protein) may be associated with TSPO availability and Aβ-accumulation already in cognitively unimpaired individuals." (PMID 37113066, 2023). "Elevated CRP levels may be associated with insulin resistance and type 2 diabetes." (PMID 37509592, 2023). "In addition to establishing CRP as a predictive risk factor for insulin resistance and the development of T2D, numerous studies also investigated whether CRP could play a role in the development of the disease state." (PMID 35883605, 2022). "As an association exists between increased PAI-1, SAA, and CRP levels and the development of insulin resistance, it is possible that these APPs may be the causative link between inflammation and insulin resistance, however, evidence supporting this hypothesis is limited." (PMID 35883605, 2022). "Moreover, the higher risk of comorbid insulin resistance in schizophrenia was associated with higher levels of CRP, suggesting that prevention or treatment of inflammation may be an advantageous option for preventing or treating comorbid IR in schizophrenia." (PMID 36090349, 2022). "In addition to routine blood tests and metabolism-related indicators, this study also assessed the association of novel markers with insulin resistance, such as C-reactive protein, neutrophil-to-lymphocyte ratio, platelet-to-lymphocyte ratio and triglyceride/HDL ratio." (PMID 36419769, 2022). "Speculated CRP causes serine phosphorylation in the insulin receptor, weakening the latter's phosphatidyl inositol 3-kinase activation and leading to the development of insulin resistance." (PMID 32280714, 2020). "Moreover, they suggest putative interactions between FGF23 and inflammatory regulatory pathways due to its association with comorbidities of psoriasis like insulin resistance, dyslipidemia, atherosclerosis, or markers of chronic inflammation like interleukin-6, CRP, TNFα, and fibrinogen." (PMID 31847236, 2019). "Furthermore, the HOMA-IR value was also positively associated with CRP concentration at baseline (R2 = 0.3288, P < 0.01) and 1 day after surgery (R2 = 0.2641, P < 0.01), indicating a possible cross-talk between insulin resistance and perioperative inflammation." (PMID 31440156, 2019). "Finally it is possible that the inflammatory responses of which CRP is a marker induce changes in conventional risk factors such as lipids, insulin and blood sugar which are related to insulin resistance as part of the metabolic syndrome and that it is these which result in the adverse consequences." (PMID 23391158, 2013). "Thus, obesity is strongly associated with OSA, insulin resistance, leptin, and CRP levels and may be the major confounding factor in the relationship of OSA to insulin resistance and cardiovascular morbidity." (PMID 20224753, 2010).
Insulin resistance (continued). "In the overall cohort, CRP concentrations, which positively correlated with BMI, insulin resistance indicators, and dyslipidemia, and negatively with estradiol, were significantly higher in SCH (p-values <0.001)." (PMID 41877931, 2026). "PCA identified two distinct latent domains explaining 69.9% of total variance: an immune-inflammatory domain (NLR, SII, ESR, CRP) and a metabolic-insulin resistance domain (TyG, AIP, METS-IR)." (PMID 42195376, 2026). "Reverse-path mediation indicated that the CHG index and the metabolic score for insulin resistance (METS-IR) jointly carried part of the high-sensitivity C-reactive protein (hs-CRP)-CircS signal." (PMID 42129743, 2026). "Clinical parameters included body mass index (BMI), waist circumference, blood pressure, lipids (LDL‐c and triglycerides), fasting glucose, HbA1c, fasting insulin (used to calculate HOMA2‐IR for insulin resistance), and C‐reactive protein (CRP)." (PMID 41559012, 2026). "BACKGROUND: The C-reactive protein-triglyceride-glucose index (CTI) has been proposed as a novel biomarker for insulin resistance and inflammation." (PMID 41937151, 2026). "Previous research has shown that Mediterranean and DASH diets—rich in unsaturated fats and fiber—reduce inflammation (e.g., CRP), support weight management, enhance antioxidant capacity, and improve insulin resistance." (PMID 41459080, 2025). "This study investigated the associations of CRF and HS during pregnancy with metabolic health outcomes (glucose intolerance, MetS, insulin resistance), and CRP at 1-year postpartum in a cohort of women with GDM." (PMID 41276872, 2025). "Whereas the protection offered by high CRP level deviates from the expected facilitation role, it further demonstrates the complexity of the relationship between CRP and the insulin resistance phenomenon." (PMID 40273152, 2025). "The anti-inflammatory effects of fasting, evidenced by reductions in hs-CRP levels, are of particular relevance in the context of T2DM, as chronic low-grade inflammation is implicated in the pathogenesis of insulin resistance and metabolic dysfunction." (PMID 40851781, 2025). "These metabolic effects have been linked to increased oxidative stress, insulin resistance, and enhanced production of proinflammatory mediators such as TNF-α, IL-6, and CRP." (PMID 40724965, 2025). "C-reactive protein is widely acknowledged as a significant indicator of inflammation that is correlated with insulin resistance (IR) and an array of metabolic disorders." (PMID 40283443, 2025). "These clinical benefits often coincide with reductions in BMI, insulin resistance (IR), and systemic inflammation, including decreases in CRP, IL-6, IL-17, and IL-23." (PMID 41020015, 2025). "The C-reactive protein-triglyceride glucose index (CTI) is a novel biomarker for assessing insulin resistance and the severity of inflammation." (PMID 41204517, 2025). "Relative to placebo treatment, green tea extract intake was associated with significantly reduced body weight and BMI values, lower serum ALT, AST, hs-CRP, and lipid levels, and enhanced insulin resistance." (PMID 39857788, 2025). "In particular, cytokines such as IL-6, IL-1β, TNF-α, and CRP contribute to the development of insulin resistance." (PMID 40283443, 2025). "While IL-6 and TNF-α actively contribute to insulin resistance and ovarian dysfunction, CRP serves as an indicator of the overall inflammatory status." (PMID 40385768, 2025). "Elevated levels of pro-inflammatory cytokines such as interleukin-6 (IL-6), C-reactive protein (CRP), and tumor necrosis factor-α (TNF-α) are associated with insulin resistance by interfering with insulin receptor signaling." (PMID 40137149, 2025). "Elevated IL-6 levels can directly impair pancreatic β-cell function and increase hepatic glucose production, while high CRP levels indicate systemic inflammation, which contributes to insulin resistance." (PMID 41523554, 2025).
Insulin resistance (continued). "As commonly used biomarkers of systemic inflammation, C-reactive protein (CRP) and white blood cell count (WBC) have been closely linked to insulin resistance, visceral adiposity, and the development of cardiovascular and cerebrovascular diseases." (PMID 40667444, 2025). "The intervention led to reductions in visceral fat, inflammatory markers (CRP), and insulin resistance (HOMA index), which were correlated with improved quality of life." (PMID 40863567, 2025). "Nevertheless, when the sample was analyzed as a whole, we did observe that CRP was positively related to body weight, visceral fat mass, and insulin resistance." (PMID 40218888, 2025). "improves levels of apolipoproteins A1 and B, oxidized low-density lipoproteins, leptin, malondialdehyde and C-reactive protein, while decreasing markers of insulin resistance." (PMID 40375997, 2025). "Fat mass strongly correlated with insulin resistance, triglycerides, and CRP, and inversely with HDL-C." (PMID 41303786, 2025). "Both early- and late-onset participants had more severe insulin resistance and CRP levels in the high HbA1c group." (PMID 40408408, 2025). "Given that sustained inflammation is a hallmark of SLE, the novel C-reactive protein (CRP)–triglyceride–glucose (TyG) index (CTI), which comprehensively reflects insulin resistance and inflammation, has emerged as a valuable biomarker." (PMID 41115075, 2025). "Elevated inflammatory markers like CRP and TNF-α in DKA and obese patients reflect the underlying inflammatory state, potentially contributing to insulin resistance." (PMID 40700071, 2025). "Research confirms higher C-reactive protein (CRP) levels in MetS patients are correlated with insulin resistance, blood pressure, poor HDL, triglycerides, and proinflammatory cytokine levels, including TNF and IL-6." (PMID 39817379, 2025). "Cortisol promotes hepatic glucose production, while inflammatory markers such as CRP can induce hepatic insulin resistance, further driving hyperglycaemia." (PMID 40580209, 2025). "CRP, produced in response to cytokines such as interleukin-6 and tumor necrosis factor-α, reflects chronic low-grade inflammation that promotes insulin resistance, endothelial dysfunction, and dyslipidemia." (PMID 41301855, 2025). "Changes in CRP were positively correlated to changes in body weight (r = 0.27, p = 0.03), visceral fat mass (r = 0.32, p = 0.01), and insulin resistance (r = 0.25, p = 0.04)." (PMID 40218888, 2025). "Using TyG as the index for insulin resistance, age, BMI, triglycerides and CRP were the significant predictors of insulin resistance in participants with past COVID-19 status." (PMID 40273152, 2025). "In terms of clinical mechanisms, reducing inflammatory markers such as CRP and TNF-α can significantly alleviate systemic inflammation, thereby decreasing the risk of complications like vascular dysfunction and insulin resistance." (PMID 40123937, 2025). "In this case, the marked reduction in CRP (17.3 → 2.7 mg/L), improved insulin resistance (HOMA-IR: 5.74 → 4.08), and resolution of hepatic steatosis (ALT: 58 → 48 U/L; AST: 48 → 26 U/L) corroborate these mechanistic pathways." (PMID 41020234, 2025). "Insulin resistance often triggers a state of low-grade chronic inflammation, activating immune cells and releasing pro-inflammatory cytokines like CRP, IL-6, and TNF-α." (PMID 40002771, 2025). "LepR, soluble leptin receptor; Adipo, adiponectin; HOMA, homeostatic model assessment of insulin resistance; Gluc, fasting glucose; CRP, high-sensitivity C-reactive protein; TMAO, trimethylamine N-oxide." (PMID 41202005, 2025). "Elevated CRP perpetuates a vicious cycle by further promoting insulin resistance and disrupting normal lipid metabolism, facilitating further weight gain and metabolic dysfunction." (PMID 41404432, 2025). "CRP can promote insulin resistance, a known pro-inflammatory state and contribute to endothelial cell inflammation." (PMID 41003011, 2025).